PTP4A3 (protein tyrosine phosphatase 4A3)
Description:
Protein tyrosine phosphatase which stimulates progression from G1 into S phase during mitosis. Enhances cell proliferation, cell motility and invasive activity, and promotes cancer metastasis. May be involved in the progression of cardiac hypertrophy by inhibiting intracellular calcium mobilization in response to angiotensin II.
Synonyms: PRL-3; PRL3; PRL-R
Tractability: Small molecule: a high-quality ligand is known. Antibody: UniProt places it where antibodies can reach, with high confidence; its Gene Ontology location is reachable by antibodies, with medium confidence. PROTAC: a small molecule that binds it is known.
Target class: Tyrosine protein phosphatase; Enzyme; Phosphatase; Protein Phosphatase
Gene: Protein-coding gene on chromosome 8 (141,391,497 to 141,432,456, forward strand). Ensembl gene ENSG00000184489.
Subcellular location: Cell membrane; Early endosome
Gene Ontology:
Molecular function: protein binding; protein tyrosine phosphatase activity
Biological process: endothelial cell migration
Cellular component: cytoplasm; nucleus; early endosome; plasma membrane
Genetic constraint (gnomAD): Loss-of-function variants: 9 observed, 17.15 expected, observed/expected ratio (o/e) 0.52, 90% interval 0.31 to 0.92. The upper end of that interval is the gene's LOEUF score, 0.92, which puts it in group 3 of 6, group 1 being the genes least tolerant of losing a copy. Missense variants: 234 observed, 242.77 expected, observed/expected ratio (o/e) 0.96, 90% interval 0.87 to 1.07. Synonymous variants: 95 observed, 97.54 expected, observed/expected ratio (o/e) 0.97, 90% interval 0.82 to 1.15.
Homologues: Orthologues: macaque PTP4A3 (100% identical), chimpanzee PTP4A3 (99% identical), mouse Ptp4a3 (97% identical), rat Ptp4a3 (97% identical), dog PTP4A3 (95% identical), pig PTP4A3 (95% identical), guinea pig PTP4A3 (93% identical), tropical clawed frog ptp4a3 (89% identical), zebrafish ptp4a3a (87% identical), zebrafish ptp4a3b (75% identical), rabbit PTP4A3 (66% identical). Paralogues in human: PTP4A1 (79% identical), PTP4A2 (75% identical), CDC14A (32% identical), CDC14B (28% identical), CDC14C (27% identical), PTPDC1 (25% identical), CDKN3 (24% identical), PALD1 (13% identical).
Diseases named in the same sentence as PTP4A3 in open-access papers:
PTP4A3 is named in the same sentence as 79 diseases in open-access papers, as found by Europe PMC text mining. Sharing a sentence is not in itself a finding about the gene and the disease. The quoted sentences say what the papers report.
colorectal cancer (10 papers, 2015 to 2025). A primary or metastatic malignant neoplasm that affects the colon or rectum. "PTP4A3 can potentially function as a potential prognostic marker in the case of LIHC (similar to the case of colorectal cancer)." (PMID 36213837, 2022). "Overexpression of PTP4A3 was found to reduce the intercellular ROS level in colorectal cancer cells." (PMID 32024182, 2020). "In conclusion, the expression of PTP4A3 and JPH1 correlates with risk of liver metastasis in colorectal cancer and breast cancer." (PMID 31748560, 2019). "The over expression of PTP4A3 has been reported in liver metastases derived from colorectal cancer as well as breast cancer, ovarian cancer, gastric cancer, esophageal carcinoma, and invasive cervical cancer." (PMID 27876019, 2016). "For example, PIM3 is a proto-oncogene that enhances pancreatic cancer growth by modulating tumor vasculogenesis; PTP4A3 can promote cancer metastasis particularly in colorectal cancers; and TOMM20 expression is associated with tumor size in gastric cancer." (PMID 26253570, 2015). "PTP4A3 was reported to activate the PI3K/AKT pathway in colorectal cancer cells." (PMID 32024182, 2020).
gastric cancer (10 papers, 2011 to 2022). A primary or metastatic malignant neoplasm involving the stomach. "Suppression of PTP4A3 caused apoptosis in prostate cancer cells and gastric cancer cells as well." (PMID 32024182, 2020). "PTP4A3 expression is higher in gastric cancer than in colon cancer, and the cutoff settings in various cancer types should be adjusted base on the immunohistochemistry of each cancer type." (PMID 34630392, 2021). "PTP4A3 is overexpressed and related to poor survival in patients with different types of cancer: breast, ovarian, liver, colon, or gastric cancer." (PMID 33498521, 2021). "PTP4A3 has been reported to have a positive relationship with HIF-1alpha in gastric cancer through gene set enrichment analysis (GSEA)." (PMID 32024182, 2020). "Elegant studies described the amplification of the PRL-3 gene (PTP4A3) in the chromosomal region 8q24.3 in colon cancer metastases, breast, and gastric carcinomas." (PMID 27911713, 2016). "Antitumor effect of PTP4A3-target monoclonal antibody was described in gastric cancer." (PMID 34630392, 2021). "Another paper has reported that PTP4A3 and HIF-1alpha are highly related in gastric cancer migration and invasion progress." (PMID 32024182, 2020). "The combination of PTP4A3 with immune cells is proposed as a predictor for immunotherapy response and prognosis in renal cancers, with potential applications in other cancer types such as NSCLC or gastric cancer as well." (PMID 34630392, 2021).
breast carcinoma (9 papers, 2011 to 2024). "For example, SHP2 was considered as an oncogene in breast cancer, leukemia, and gliomas, and PTP4A3 is an oncogene in breast, gastric, and colon cancer." (PMID 34660327, 2021). "The PTP4A3 gene is overexpressed in 29% of all basal-like breast cancers and may be a prognostic indicator for poor breast cancer patient survival." (PMID 34884670, 2021). "We measured the expression of PTP4A3 and JPH1 in a breast cancer cohort by qPCR and used it to calculate the risk score in a series of 463 tumors for which the time and site of relapse were known (271 hormone receptor-positive, 86 triple-negative and 106 HER2-positive)." (PMID 31748560, 2019). "A DNA vaccine targeting PTP4A3 triggered high expression of interferon-γ and TNF-α in breast cancer through the CTL and T helper type 1 cells immune response and also stimulated the accumulation of PTP4A3 antibody in immunized mice." (PMID 34630392, 2021). "In another study on breast cancer, it was found that PTP4A3 can induce the transformation of normal cancer cells into stem-like cells by competitively binding to MEF2A with HDAC4 (histone deacetylase 4), a process independent of PTP4A3’s phosphatase activity." (PMID 38611852, 2024).
ovarian carcinoma (8 papers, 2015 to 2024). A malignant neoplasm originating from the surface ovarian epithelium. "This highlights the potential therapeutic relevance of targeting PTP4A3 for ovarian cancer treatment." (PMID 40836974, 2024). "A previous study reported ovarian cancer cells with PTP4A3 inhibited resulted in cell proliferation suppression." (PMID 32024182, 2020). "Studies with patient-derived tumor samples indicate a high level of expression of protein-tyrosine phosphatase 4A (PTP4A, also known as PRL) family members, and particularly PTP4A3 in ovarian cancers." (PMID 29492190, 2018). "Prenylation of PTP4A3 at Cys170 promotes AP accumulation via the canonical PIK3C3-BECN1 autophagy pathway, which promotes ovarian cancer cell proliferation." (PMID 39883197, 2024). "Prenylation of PTP4A3 at Cys170 promotes AP accumulation via the canonical PIK3C3-BECN1 autophagy pathway, which is beneficial for the proliferation of ovarian cancer cells." (PMID 39883197, 2024). "Monitoring PTP4A3 expression levels and STAT3 phosphorylation status in tumor tissues could be implemented to indicate personalized phosphatase inhibitor treatment for ovarian cancer." (PMID 40836974, 2024).
leukemia (6 papers, 2017 to 2021). A malignant (clonal) hematologic disorder, involving hematopoietic stem cells and characterized by the presence of primitive or atypical myeloid or lymphoid cells in the bone marrow and the blood. "Compared with adjacent normal tissues, PTP4A3 mRNA levels were elevated in most cancer types, including breast, colorectal, esophageal, head and neck, kidney, leukemia, liver, melanoma, myeloma, pancreatic, prostate, and sarcoma." (PMID 34630392, 2021). "PTP4A3 is overexpressed in leukemia cells and is related to cell proliferation." (PMID 32024182, 2020). "Here, we determined that the protein tyrosine phosphatase 4A3 (PTP4A3 or PRL-3) plays a critical role in T-ALL initiation and progression by promoting leukemia cell migration." (PMID 32001668, 2020). "Furthermore, two recent studies showed a novel cooperative activity of E/R with the antiapoptotic protein BCL2 and the protein tyrosine phosphatase 4A3 (PTP4A3), although the impact on leukemia progression needs to be further explored." (PMID 28418909, 2017).
myeloma (6 papers, 2011 to 2025). "We have previously found that phosphatase of regenerating liver-3 (PTP4A3/PRL-3) has oncogenic properties in multiple myeloma (MM) and acute lymphoblastic leukemia (ALL)." (PMID 29651360, 2018). "Only a few studies report differences in expression levels of PTP4A3 in ALL and myeloma subgroups, based on gene expression profiling." (PMID 22028901, 2011).
uveal melanoma (6 papers, 2012 to 2021). A melanoma derived from melanocytes of the uveal tract. "We derived and validated a prognostic score that predicted relapse in uveal melanoma based on the weighted expression of only two genes (PTP4A3 and JPH1) and applied it to the prediction of liver relapse in other malignancies." (PMID 31748560, 2019). "High expression levels of Protein Tyrosine Phosphatase 4A3, a dual phosphatase, is highly predictive of metastasis development and PTP4A3 overexpression in uveal melanoma cells increases their in vitro migration and in vivo invasiveness." (PMID 24376839, 2013). "We therefore suggested that PTP4A3 function in uveal melanoma metastasis may be related to an embryonic role during neural crest cell migration." (PMID 24376839, 2013). "Thus, understanding PTP4A3 mechanism of action during NC migration may provide insight into PTP4A3 related migratory and invasive phenotypes in human uveal melanoma pathology." (PMID 24376839, 2013). "In addition, high PTP4A3 expression was correlated with decreased OS and DFS in uveal melanoma (UVM)." (PMID 34630392, 2021).
colon carcinoma (5 papers, 2011 to 2021). "To investigate the role of Ptp4a3 in malignancy, we used the most commonly studied murine colitis-associated colon cancer model." (PMID 23555575, 2013). "Because human PTP4A3 is been implicated in the pathogenesis of human metastatic colorectal cancer, we investigated the effects of Ptp4a3 deletion in a mouse model of colon cancer." (PMID 23555575, 2013). "Notably, mice deficient for Ptp4a3 had >50% reduction in tumor formation providing further evidence that Ptp4a3 is a key mediator of colon cancer progression." (PMID 23555575, 2013). "Studies in PTP4A3 transgenic mice have shown that high expression of PTP4A3 promotes colitis-related colon cancer, shortens telomeres, and increases expression of H3K9Me, a hallmark of genomic instability." (PMID 34630392, 2021). "Stable expression of PTP4A3 elevated the secretion level and mRNA level of IL-1alpha in colon cancer cell lines." (PMID 34630392, 2021). "Many human cancers express high PTP4A3 levels including tumors of the colon, breast, ovary, liver, stomach, and stroma, and elevated PTP4A3 expression often correlates with increased tumor invasiveness and poor prognosis." (PMID 23555575, 2013). "Ptp4a3-null mice developed 50% fewer colon tumors than wildtype mice after exposure to azoxymethane and dextran sodium sulfate." (PMID 23555575, 2013). "While the role of Ptp4a3 in colon cancer is traditionally thought to involve late-stage tumors and metastasis, this finding suggests a potential role in early-stage disease and tumorigenesis." (PMID 23555575, 2013). "To explore a potential functional role for Ptp4a3 in tumor formation, we subjected mice to a widely used AOM-DSS model of colitis-associated colon cancer." (PMID 23555575, 2013). "These primary tumors displayed consistently higher levels of Ptp4a3 relative to normal colon epithelium – similar to what is seen in human colon cancer patients." (PMID 23555575, 2013). "Because high expression of PTP4A3 has been reported in human primary colon tumors, we examined Ptp4a3 expression in the mouse model of colon cancer." (PMID 23555575, 2013). "In contrast, PTP4A3 was readily detectable, but variable, in colon tumor samples." (PMID 23555575, 2013). "Additionally, Ptp4a3 has been identified as a direct regulatory target of TGFβ signaling in colon cancer cells." (PMID 23555575, 2013). "Interestingly, Ptp4a3 has been identified as a direct regulatory target of TGFβ signaling in colon cancer." (PMID 23555575, 2013). "We next examined lysates obtained from both wildtype and Ptp4a3-null colon tumors." (PMID 23555575, 2013). "In the current study, we provide evidence that the Ptp4a3 mRNA and PTP4A3 protein levels are increased soon after exposure to AOM, the initiating step in our colon cancer model." (PMID 23555575, 2013).
glioma (4 papers, 2020 to 2024). A benign or malignant brain and spinal cord tumor that arises from glial cells (astrocytes, oligodendrocytes, ependymal cells). "Meanwhile, Notch1 pathway‐related genes, including Maml2, Ccn3, Fat4, Cdh6, and Ptp4a3, exhibited similar expression trends and may be intimately linked to glioma development." (PMID 39544152, 2024). "High PTP4A3 expression was also correlated with decreased OS in acute myeloid leukemia (AML), lower grade glioma (LGG), LUSC and STAD." (PMID 34630392, 2021).
melanoma (4 papers, 2011 to 2024). A malignant, usually aggressive tumor composed of atypical, neoplastic melanocytes. "PTP4A3 restricts transcription in melanoma through the DDX21-MITF axis." (PMID 34630392, 2021). "Furthermore, PTP4A3 showed a correlation with the expression of several proteases such as ADAM10, which is well-known to be elevated in melanoma metastases, being associated with multiple adhesion molecules that play a crucial role in the development of malignant melanoma." (PMID 39596556, 2024). "Moreover, PTP4A3 correlated with the expression of several proteases like ADAM10 (A Disintegrin and Metalloproteinase 10), which is upregulated in melanoma metastases and related to many adhesion molecules that have a central role in developing malignant melanoma." (PMID 35480119, 2022).
hepatocellular carcinoma (3 papers, 2011 to 2021). A malignant tumor that arises from hepatocytes. "The expression level of PTP4A3/PRL-3 mRNA was evaluated in 13 hepatoma cell lines." (PMID 23064776, 2013).
liver cancer (3 papers, 2018 to 2022). An epithelial or non-epithelial malignant neoplasm that arises from the liver. "Due to the important role of PTP4A3 in cancers, a PRL-zumab was generated by the Zeng group and was shown to specifically inhibit PTP4A3-positive liver cancer cell in vivo, and recruit B cells, NK cells and macrophages to the PTP4A3-positive tumor microenvironment." (PMID 34630392, 2021). "The results reveal whether PTP4A3 can function as a potential therapeutic target for liver cancer." (PMID 36213837, 2022).
acute myeloid leukemia (2 papers, 2020 to 2021). Acute myeloid leukemia (AML) is a group of neoplasms arising from precursor cells committed to the myeloid cell-line differentiation. "Several studies have also shown that PTP4A3 participates in the development of acute myeloid leukemia and chronic myeloid leukemia." (PMID 32024182, 2020).
esophageal carcinoma (2 papers, 2016). A primary or metastatic malignant neoplasm involving the esophagus. "PRL-3 is encoded by the gene PTP4A3 and its expression in cancer cells was shown to be associated with the cells’ ability to metastasize and with a poor prognosis in multiple cancers, including breast, colon, gastric, ovarian and esophageal carcinomas." (PMID 27036022, 2016).
lung carcinoma (2 papers, 2016 to 2022). "Previous studies proved that the knockdown of PTP4A3 inhibited cell migration and invasion of lung cancer cell lines." (PMID 35992814, 2022).
ovarian serous cystadenocarcinoma (2 papers, 2018 to 2021). A malignant serous cystic epithelial neoplasm arising from the ovary. "PTP4A3 expression and OS were not correlated in BLCA, chRCC, KIRC, pRCC (KIRP), ovarian serous cystadenocarcinoma (OV), PRAD, uterine corpus endometrial carcinoma (UCEC) and uterine carcinosarcoma (UCS)." (PMID 34630392, 2021).
papillary renal cell carcinoma (2 papers, 2021 to 2022). A rare subtype of renal cell carcinoma, arising from the renal tubular epithelium and showing a papillary growth pattern, which typically manifests with hematuria, flank pain, palpable abdominal mass or nonspecific symptoms, such as fatigue, weight loss or fever. "PTP4A3 expression was associated with the infiltration of dendritic cells in papillary renal cell carcinoma." (PMID 34630392, 2021). "PTP4A3 was also consider as a prognostic biomarker correlated with immune infiltrates in papillary renal cell carcinoma." (PMID 36081847, 2022). "PTP4A3 expression correlated genes involved in B cells, monocytes, M1 macrophages, Th2 and Treg cells in papillary renal cell carcinoma." (PMID 34630392, 2021). "We further confirmed that the infiltration of B cells and CD8+ T cells was associated with poor prognosis in papillary renal cell carcinoma patients, consistent with the prognostic role of PTP4A3 in papillary renal cell carcinoma." (PMID 34630392, 2021). "Using the GEPIA and PrognoScan databases, the independent prognostic role of PTP4A3 was confirmed in clear cell renal cell cancer and papillary renal cell cancer." (PMID 34630392, 2021). "Comprehensive analysis of immune infiltration in the TIMER database correlated PTP4A3 expression with the infiltration of B cells, CD8+ T cells, CD4+ T cells and neutrophils in both clear cell renal cell carcinoma and papillary renal cell carcinoma." (PMID 34630392, 2021).
prostate carcinoma (2 papers, 2016 to 2020). A carcinoma that arises from epithelial cells of the prostate gland. "The suppression of PTP4A3 induced growth inhibition of the prostate cancer cell lines in vitro." (PMID 32024182, 2020).
triple-negative breast carcinoma (2 papers, 2020 to 2024). An invasive breast carcinoma which is negative for expression of estrogen receptor (ER), progesterone receptor (PR), and human epidermal growth factor receptor 2 (HER2). "PTP4A3 depletion caused apoptosis elevated in triple-negative breast cancer." (PMID 32024182, 2020).
acute T-cell lymphoblastic leukemia (1 paper, 2024). "Our research in acute T-cell lymphoblastic leukemia (T-ALL) has shown that although PTP4A3 can influence the phosphorylation levels of Src kinase, subsequent studies have revealed that its oncogenic role in T-ALL does not depend on its enzymatic activity." (PMID 38611852, 2024).
asthma (1 paper, 2022). "Commonly downregulated to PTSD and severe asthma were ORMDL3 (2.2E-2, 1.9E-3, 2.7E-3, 3.9E-3), PTP4A3 (2.6E-3, 2.3E-2, 4.5E-3, 5.2E-3), SHISA4 (1.1E-2, 4.4E-2, 9.8E-3, 6.2E-3), and TPPP3 (2.2E-2, 1.1E-2, 3.1E-3, 2.7E-2)." (PMID 36206293, 2022).
bone marrow failure (1 paper, 2011). "Challenges for the future are to determine the dose-effect of PTP4A3 expression in myeloid development and to extend the screens to additional myeloid neoplasms, e.g., myelodysplasia, therapy-related AML, AML secondary to bone marrow failure and myeloproliferative disorders." (PMID 22028901, 2011).
bone metastasis (1 paper, 2016). Transfer of a neoplasm from its primary site to bones. "Finally, multivariate analysis including the panel of five CTC-biomarkers in combination with the presence of bone metastasis resulted in GAPDH, NOTCH1 and PTP4A3 as independent predictors of PFS; GAPDH and ITGB3 showed predictive value for OS." (PMID 27901069, 2016).